BCOR (BCL6 corepressor)
Diseases named in the same sentence as BCOR in open-access papers (continued):
Sharing a sentence is not in itself a finding about the gene and the disease.
CNS tumors (22 papers, 2019 to 2025). "Tumors with BCOR tandem duplications including CNS tumors have been found to be associated with a poor prognosis." (PMID 30526817, 2019). "Based on our index case and the 35 cases found in the literature, we suggest the archetypical histological and molecular features of “CNS tumor with BCOR/BCOR(L1)-fusion”." (PMID 38637838, 2024). "BCOR ITD-CNS tumors seem to have a higher rate of recurrence than EP300-BCOR-fused CNS tumors (65% vs. 53%)." (PMID 39409964, 2024). "After the first description of CNS tumor with BCOR ITD, other tumors with overlapping morphological and immunohistochemical features, but harboring fusions of BCOR with either EP300 or its paralog CREBBP, instead of BCOR ITD, have been reported in the CNS." (PMID 38216991, 2024). "BCOR fusions have also been identified in pediatric CNS tumors with two different gene fusion partners: EP300 and CREBBP." (PMID 39409964, 2024). "The core characteristic of “CNS tumor with BCOR/BCOR(L1)-fusion” is defined as predominant presence of a BCOR fusion with often EP300 as the fusion partner and/or characteristic CNV." (PMID 38637838, 2024). "In a comparative systematic review of the literature, we found 35 published cases of neuroepithelial CNS tumors that either carried a BCOR/BCOR(L1)- or other related fusions, or had a methylation profile compatible with CNS tumors with BCOR/BCOR(L1)-fusion." (PMID 38637838, 2024). "These tumors exhibit a DNA methylation profile close to that of CNS tumors with BCOR ITD, suggesting a similarity between the two." (PMID 38216991, 2024). "BCOR internal tandem duplication (ITD) has already been included in the WHO CNS5 for the diagnosis of “CNS tumor with BCOR ITD”." (PMID 39409964, 2024). "Two newly introduced entities are FOXR2-activated CNS neuroblastoma and CNS tumor with BCOR internal tandem duplication (ITD) (WHO Classification of Tumours Editorial Board, 2021)." (PMID 38544524, 2024). "Within the 2021 classification of CNS tumors, two novel embryonal tumors have been added: CNS neuroblastoma, FOXR2-activated and CNS tumor with BCOR internal tandem duplication." (PMID 37658995, 2024). "Two CNS tumors with fusions between CREBBP, or its paralog EP300, and BCORL1, and approximately twenty CNS tumors with CREBBP/EP300::BCOR fusions have been reported to date." (PMID 38216991, 2024). "CNS tumor with BCOR internal tandem duplication (ITD) is a malignant CNS neoplasm that has an ITD in exon 15 of the BCOR gene." (PMID 38544524, 2024). "It is possible to distinguish CNS tumors with BCOR ITD from other CNS tumors by DNA methylation profiling and gene expression patterns." (PMID 38544524, 2024). "The inconstant immunopositivity for BCOR constitutes a supplemental difficulty when suggesting the diagnosis for the CNS tumor with BCOR fusion in adults." (PMID 36782314, 2023). "Three patients had the diagnosis of a CNS tumour with BCOR ITD both by histopathology and by methylation." (PMID 36895035, 2023). "CNS tumors with BCOR internal tandem duplication are another newly recognized embryonal tumor subtype." (PMID 36617415, 2023). "An EP300-BCOR fusion has been reported in rare pediatric CNS tumors and appears to define a distinct subtype from the BCOR ITD." (PMID 36617415, 2023). "In a single case, PLAGL1 was fused to EP300, a fusion partner known from ‘CNS tumors with BCOR alteration’." (PMID 34355256, 2021). "The 2021 update to the World Health Organization (WHO) classification of CNS tumors saw the incorporation of several new CNS embryonal tumors subtypes, including: cribriform neuroepithelial tumor; CNS neuroblastoma, FOXR2-activated; and CNS tumor with BCOR internal tandem duplication." (PMID 38500181, 2024). "CNS tumors with BCOR ITDs also harbor a specific DNA methylation profile." (PMID 37658995, 2024). "For infant-type hemispheric glioma, the differential diagnosis may include DIG/DIA, supratentorial ependymoma, astroblastoma MN-1 altered, and CNS tumor with BCOR-ITD." (PMID 39440342, 2024).
CNS tumors (continued). "In the setting of a CNS tumor, the presence of a BCOR ITD may provide diagnostic information, defining a molecular entity in the WHO Classification of CNS Tumours known as CNS Tumour with BCOR ITD." (PMID 37686670, 2023). "Thus, all CNS NB-FOXR2s, CNS tumours with BCOR ITDs and ETMRs were well classified including one ETMR without the microRNA cluster on chromosome 19 (C19MC)." (PMID 36895035, 2023). "CNS tumors from the EP300::BCOR fusion methylation class in adults may be added to the future WHO classification." (PMID 36782314, 2023). "In addition, other CNS tumors harboring a BCOR/BCORL1 fusion, which are defined by a distinct DNA-methylation profile, have been recently identified in the literature but clinical, radiological and histopathological data remain scarce." (PMID 36782314, 2023). "CNS tumors with BCOR ITD manifest branching arcuate capillary network, myxoid background, strong nuclear BCOR expression, and related molecular findings." (PMID 39440342, 2024). "Interestingly, the DNA methylation classification provides a specific MC for BCOR/BCORL1-fused CNS tumors, distinct from the BCOR-ITD CNS tumors." (PMID 39409964, 2024). "Similarly, the BCOR staining cannot differentiate between HGNET-BCOR-ITD and CNS tumor with BCOR/BCOR(L1)-fusion, since a majority of HGNET-BCOR-ITD also show a nuclear BCOR expression." (PMID 38637838, 2024). "We describe a rare case of a CNS tumor in a 45-year-old man with histopathological and immunohistochemical features overlapping the CNS tumor with BCOR internal tandem duplication (ITD) but lacking BCOR immunostaining and BCOR ITD." (PMID 38216991, 2024). "However, CNS tumors with BCOR ITD seem to be more circumscribed than their counterparts having a BCOR fusion (n = 41/47 and n = 4/8 respectively)." (PMID 36782314, 2023). "Recently, cases of CNS tumors harboring EP300::BCOR(L1) fusions (21 reported cases) were described, sharing histopathological features with CNS tumors having BCOR ITD, but not the same methylation class." (PMID 36782314, 2023). "BCOR mRNA expression in primary CNS tumors was evaluated using public data, and we confirmed the upregulation in CNS-BCOR ITD (nine samples) compared to all other CNS tumor types (12 entities, 131 samples) (p value < 0.0001, Mann–Whitney test)." (PMID 33920124, 2021). "Moreover, it seems like alternative fusions (CREBBP::BCOR and MEAF6::CXXC5) may be encountered as a subset of CNS tumors within the EP300::BCOR(L1) methylation class." (PMID 36782314, 2023). "BCOR-ITD is not present in any of the CNS tumors with BCOR/BCOR(L1)-fusion and this helps differentiating from HGNET-BCOR-ITD." (PMID 38637838, 2024). "In contrast to 100% of reported CNS tumors with BCOR ITD, tumors with BCOR fusion do not all exhibit an overexpression of the BCOR protein by immunohistochemistry (present in 43% of reported cases)." (PMID 36782314, 2023). "While the versions 12.5 showed a calibrated score of 0.65 for the subtype “CNS tumor with BCOR/BCOR(L1)-fusion”, the versions 12.8 showed a discrepant result with calibrated score of 0.91 for the subtype HGNET-BCOR-ITD; however, PCR analysis showed no BCOR-ITD." (PMID 38637838, 2024). "However, according to the authors personal unpublished experience BCOR immunoreactivity is not specific for HGNET-BCOR tumors and may be also encountered in other CNS tumors." (PMID 30526817, 2019).
hematological disorders (9 papers, 2020 to 2025). "Recent whole-exome sequencing efforts have identified somatic BCOR mutations in various hematological diseases." (PMID 33468080, 2021). "Previous research has shown that ITP patients harboring mutations in genes such as DNMT3A, TET2, ASXL1, BCOR, PIGA, and U2AF1 tend to progress into other clonal hematologic disorders, leading to treatment ineffectiveness." (PMID 40574285, 2025). "Relationship between AKT3 and mutations related to MDS or MPN hematological disorders The MDS- or MPN-related mutations affect genes involved in different molecular aspects of gene expression including RNA splicing (SRSF2, U2AF1 and SF3B1), chromatin remodeling (ASXL1) and gene transcription (BCOR)." (PMID 38528080, 2024). "Among them, PRC 1.1, comprising PCGF1, RING1A/B, BCOR or BCORL1, and KDM2B, is of particular interest because of its distinct functions in hematopoietic stem cells and hematologic malignancies." (PMID 33374737, 2020).
hematologic cancers (3 papers, 2017 to 2022). "In addition, other genes known to be affected by somatic mutations in hematologic cancers were also found from the WES data, such as JAK3, CREBBP, BCOR, and so on." (PMID 28410228, 2017). "BCL6 Corepressor (BCOR) is an epigenetic regulator whose alterations recur in solid and hematologic tumors." (PMID 35494081, 2022).
hematologic neoplasms (1 paper, 2024). "However, in a recent paper, the BCOR mutation has been correlated with a worse prognosis in hematologic neoplasms." (PMID 39062853, 2024).
BCOR also shares sentences with these, for which no sentence is quoted: malignant peripheral nerve sheath tumor (3 papers); osteosarcoma (3); acute leukemia (2); Anophthalmia (2); Burkitt lymphoma (2); chondrosarcoma (2); Down syndrome (2); endometrial tumors (2); glioblastoma (2); glioneuronal tumor (2); neurodevelopmental disorder (2); non-small cell lung carcinoma (2); ossifying fibromyxoid tumor (2); perivascular epithelioid cell tumor (2); pineoblastoma (2); prostate carcinoma (2); schwannoma (2); undifferentiated sarcoma (2); acute lymphoblastic leukaemia (1); adrenocortical carcinomas (1); anaplastic large cell lymphoma (1); anaplastic oligodendroglioma (1); and heart disorders (1); anemia (1); angioimmunoblastic T-cell lymphoma (1); angiomatoid fibrous histiocytoma (1); aniridia (1); Arterial thrombosis (1); atypical lipomatous tumor (1); atypical teratoid rhabdoid tumor (1).
A further 60 diseases each share a sentence with BCOR in 1 paper.